LEP (leptin)
Diseases named in the same sentence as LEP in open-access papers (continued):
Sharing a sentence is not in itself a finding about the gene and the disease.
Sepsis (continued). "Compared to the SH group, sepsis resulted in decreased plasma adiponectin levels, while leptin concentrations increased several fold post-CLP." (PMID 33223959, 2020). "The levels of leptin seem to rapidly increase in acute inflammatory conditions, such as cholecystectomy and sepsis, particularly favored by cytokines such as TNF-α, IL-6, and IL-1β." (PMID 30949073, 2019). "In mouse endotoxemia and cecal ligation puncture models of sepsis, elevated levels of leptin and soluble leptin receptor have been observed." (PMID 31877773, 2019). "More recently, leptin that is produced and secreted by several tissues, especially adipose tissue, was increased and was able to predict poor outcomes in sepsis patients." (PMID 30913261, 2019). "In a longitudinal study including patients with sepsis, leptin levels were significantly higher compared with controls and showed a positive correlation with insulin levels and insulin resistance." (PMID 31569348, 2019). "For this reason, the participation of leptin in sepsis and endotoxemia has received increasing attention during the last decade." (PMID 30618812, 2018). "In sepsis, the leptin infusion via intracerebroventricular route into the CNS of ob/ob mice significantly reduced IL-6 levels in serum thereby controlled systemic inflammation and improved survival." (PMID 29868503, 2018). "Accordingly, leptin is produced and secreted by adipose tissue; obese subjects frequently exhibit resistance to sepsis and endotoxemia." (PMID 30618812, 2018). "Lipopolysaccharide-induced acute lung injury is lessened by exogenous leptin administration, and hyperleptinemia generates resistance to endotoxemia, improving sepsis survival and modulating the immune response." (PMID 30618812, 2018). "Because NO regulates vasorelaxation, which contributes to the regulation of blood pressure, it is plausible that leptin exerts actions that modulate NO biodisposition to maintain blood pressure during sepsis." (PMID 30618812, 2018). "In fact, toxicity exerted by TNF-α is blunted by endogenous serum leptin, which promotes a protective effect during systemic inflammation, such as sepsis." (PMID 30618812, 2018). "Thus, elevated circulating leptin concentrations during sepsis syndrome could maintain blood pressure at normal due to its hypertensive effects, which counteract the hypotension caused by sepsis." (PMID 30618812, 2018). "In agreement with the evidence that shows the beneficial actions of leptin during sepsis and endotoxemia, the alteration of the leptin receptor has been associated with higher mortality in patients with peritonitis." (PMID 30618812, 2018). "Equalization in leptin levels between sexes have also been reported in children with sepsis and that children with higher increases in leptin levels had an unfavourable outcome." (PMID 28919840, 2017). "Circulating levels of leptin and adiponectin were determined in stored plasma, and their impact on a future sepsis event and its outcome was evaluated." (PMID 28919840, 2017). "Here we report that high levels of circulating leptin at baseline independently predicted a first-ever sepsis event, possibly with a sex-related difference." (PMID 28919840, 2017). "Our results are consistent with earlier reports showing that high leptin levels are related to better outcome in acute sepsis." (PMID 28919840, 2017). "In contrast, we found that high leptin levels at baseline predicted sepsis with an unfavourable outcome." (PMID 28919840, 2017). "Altered circulating levels of insulin, leptin, resistin, and PAI-1 have been previously indicated in acute settings of sepsis and these molecules have been implicated in sepsis pathogenesis." (PMID 29326685, 2017). "Median plasma adiponectin levels were lowered and resistin and leptin levels elevated in sepsis compared with preseptic plasma levels." (PMID 27601939, 2016). "Compared with preoperative blood samples, adiponectin was lowered and resistin and leptin elevated in sepsis." (PMID 27601939, 2016).
Sepsis (continued). "The differences in circulating ghrelin and leptin levels in sepsis likely leads to altered immune regulation." (PMID 25844479, 2015). "Both are found to increase in sepsis, with ghrelin suggested to inhibit leptin-induced cytokine expression." (PMID 25844479, 2015). "Leptin has been shown to be elevated in early stages of inflammation and in the exacerbation of sepsis mortality." (PMID 25984763, 2015). "Hyperleptinemia improves resistance to endotoxin and plasma leptin levels are found to be increased in survivors of acute sepsis." (PMID 25844479, 2015). "Leptin has specific effects on T-lymphocytes and monocytes and improves cytokine response and demonstrated survival benefits during sepsis." (PMID 25844479, 2015). "In our study, obese mice revealed a stabile body temperature in sepsis benefited by elevated basic leptin levels." (PMID 25844479, 2015). "The monitoring of serum leptin levels in septic patients is important for the early diagnosis of sepsis and the differentiation between sepsis and SIRS." (PMID 24669245, 2014). "Leptin is reported to have both beneficial and detrimental effects for the host in the setting of sepsis." (PMID 25398383, 2014). "The present study was conducted to determine the role of serum leptin in the early diagnosis of sepsis and to explore its correlation with additional biomarkers of sepsis and/or multiple organ failure." (PMID 24669245, 2014). "The leptin concentrations in patients with sepsis were significantly higher than those of the patients in the control group (11.67±0.72 versus 4.82±0.36 mg/dl) (P<0.001)." (PMID 24669245, 2014). "Mouse endotoxaemia and caecal ligation puncture models of sepsis present with elevated levels of leptin, while exogenous administration of leptin to endotoxaemic mice increases mortality." (PMID 24578293, 2014). "The elevation of leptin levels was particularly marked in the sepsis group, in which the mean serum leptin concentrations at admission were 16.07 μg/l in males and 9.1 μg/l in females (P=1.4E-6)." (PMID 24669245, 2014). "The leptin levels in male patients were higher than those in female patients, particularly in the sepsis group." (PMID 24669245, 2014). "Based on the finding that leptin serum concentrations were higher in the septic group than in the control group, the ability of serum leptin levels to identify patients with sepsis in the medical ICU setting was investigated." (PMID 24669245, 2014). "Septic patients displayed significantly higher leptin serum concentrations compared with those of the non-sepsis group (mean concentration, 11.67 versus 4.824 mg/dl; P<0.001)." (PMID 24669245, 2014). "Recent investigations into the alterations in response to sepsis in these animal models have focused on hormonal mediators, including leptin and adiponectin." (PMID 23957291, 2013). "Although patients with high levels of serum leptin were shown to suffer from sepsis and other inflammatory diseases, some reports suggest an immune-optimizing and pro-survival role of leptin in mouse models of sepsis." (PMID 23383125, 2013). "In patients suffering from severe sepsis leptin serum levels remained at the same level from days 1 to 5 in those patients without treatment of DAA." (PMID 22973876, 2012). "The specific mechanism or even benefit of DAA administration in the time course of sepsis towards leptin needs further ongoing research." (PMID 22973876, 2012). "Leptin appears to be involved in the pathogenesis of a systemic inflammatory response during sepsis." (PMID 22973876, 2012). "As far as we know, this is the first report of the association between LEP and LEPR genetic polymorphisms and death, in any form of sepsis." (PMID 21943151, 2011). "These authors suggest that the protective effect of LEP in sepsis occurs through CNS signalling that coordinates an appropriate immune response." (PMID 21943151, 2011).
Sepsis (continued). "Earlier reports suggested that high lepin levels are associated with increased survival in sepsis and septic shock, several other reports -such as our study- fail to show a correlation between leptin and sepsis." (PMID 20825686, 2010). "Recently, several reports have identified a role for leptin in regulating immune function while leptin levels acutely increase during inflammation, infection and sepsis." (PMID 21040518, 2010). "Low levels of circulating RBP4 and leptin were previously observed after burn injury or trauma or both, and low levels of adiponectin were reported in rats with sepsis." (PMID 19589139, 2009). "Earlier studies on leptin levels in the acute phase (first 24 hours) of sepsis describe a sepsis-induced elevation in leptin." (PMID 19589139, 2009). "Leptin levels were found to be elevated in patients with sepsis and low leptin levels in patientswith sepsis and septic shock are significantly associated withhigh mortality." (PMID 17497033, 2007). "A possible explanation for the biphasic response of leptin found in patients during the course of sepsis may be related to the increased release of inflammatory cytokines during the acute phase." (PMID 39838305, 2025). "In critically ill patients with sepsis, another study reported that “lower serum leptin at enrollment and day 7 was independently associated with 28-day mortality”, and leptin levels were higher in survivors than in non-survivors." (PMID 39062875, 2024). "In sepsis patients (56% male), serum leptin levels were higher in survivors." (PMID 37238973, 2023). "This is the first study we are aware of that demonstrates an association between cord blood IL-6 and leptin in appropriate for gestational age infants without sepsis." (PMID 35197933, 2022). "Monitoring serum leptin levels in critically ill patients could be of great value for early diagnosis and prognosis of sepsis." (PMID 33907162, 2021). "Because few human studies have been reported in literature, there is a need for further studies to demonstrate the specificity and sensitivity of leptin in the early diagnosis of sepsis and the need to measure serum leptin levels in routine evaluation of the critical patient." (PMID 33907162, 2021). "At the time of onset of sepsis, increased leptin levels were associated with better survival in men, but not in women." (PMID 35052684, 2021). "Emerging data from animal models and humans indicates that leptin could control the systemic immune defense response and further suggests the possible therapeutic potential of exogenous leptin administration in infectious diseases and sepsis." (PMID 33907162, 2021). "Better understanding of the pathophysiology of sepsis and the implication of circulating total leptin in this process could help physicians in managing this life-threatening condition." (PMID 33907162, 2021). "Concentrations of leptin also increase in bronchoalveolar lavage samples after endotoxin inhalation in both humans and mice, in intestinal epithelium upon infection or in animal model of sepsis." (PMID 33804765, 2021). "Leptin administration has a protective role against the effects of sepsis and endotoxemia." (PMID 33907162, 2021). "Thus, we propose that S100A9 and leptin represent tools to reduce calprotectin with putative beneficial outcomes in several maladies, including sepsis and autoimmunity." (PMID 31391467, 2019). "Further experiments are needed to elucidate whether leptin modulates TRL-4 expression or activity to generate protection against sepsis." (PMID 30618812, 2018). "Considering that muscle mass is severely compromised during severe sepsis and endotoxemia, we evaluated whether leptin administration protects against muscle mass wasting during endotoxemia." (PMID 30618812, 2018). "With respect to the beneficial effects of leptin administration during sepsis, it is possible to hypothesize that leptin acts on the excitability of the POMC and NPY/AgRP neurons." (PMID 30618812, 2018).
Sepsis (continued). "Here, we showed for the first time, that leptin administration before sepsis induction reduced both the severely decreased systolic blood pressure and increased heart rate that are characteristically observed during endotoxemia such that these parameters were nearly at control levels." (PMID 30618812, 2018). "In humans, it associated with pancreatitis, sepsis and septic shock suggests that non-physiological excess levels of leptin are toxic to the host system due to excessive proinflammatory cytokine response and inflammation, which causes tissue damage." (PMID 29868503, 2018). "Taken together, here we showed a leptin-based potential preventive treatment against sepsis." (PMID 30618812, 2018). "In contrast, survival curves from the endotoxemic rats (vehicle-treated/endotoxemic rats), showed a significant difference compared to the vehicle-treated/saline-treated and leptin-treated/saline-treated rats, as expected with the high mortality score of sepsis." (PMID 30618812, 2018). "It is interesting that the serum leptin levels are increased during sepsis and endotoxemia." (PMID 30618812, 2018). "Immune response modulation during sepsis is a major feature of importance in leptin administration." (PMID 30618812, 2018). "The beneficial actions of leptin during sepsis could be mediated by regulation of the expression of the endotoxin receptor toll-like receptor-4 (TRL-4) and modulation of its activity." (PMID 30618812, 2018). "Leptin appears to play a regulatory role in the immune system in sepsis." (PMID 28859605, 2017). "Furthermore, the samples from the pre-sepsis investigation do represent population-based levels and we have previously shown that individual leptin levels are stable over long periods of time in men and women and in different ethnicities." (PMID 28919840, 2017). "High circulating levels of leptin predicted a first-ever sepsis event (OR 2.04, 95% CI 1.30–3.2, P = 0.002) and retained predictive value after adjustment for BMI (OR 1.89, 95% CI 1.14–3.13, P = 0.01) and in the fully adjusted model (OR 1.77, 95% CI 1.04–3.00, P = 0.03)." (PMID 28919840, 2017). "There is a graded response between high levels of leptin at baseline and sepsis severity." (PMID 28919840, 2017). "Further, resistin and leptin levels are elevated in sepsis following major surgery." (PMID 27601939, 2016). "However, leptin also exhibits pro-inflammatory and protective functions, and is additionally involved in the pathogenesis of a systemic inflammatory response during sepsis by several interactions towards T cells, monocytes, and cytokine production." (PMID 27601939, 2016). "If ghrelin and leptin counteract one another under conditions of inflammation and sepsis, then additional ghrelin treatment after CLP could lead to a reactive leptin elevation in an attempt to maintain the balance between both regulatory components." (PMID 25844479, 2015). "Increased leptin levels in sepsis should be responsible for improved survival and immunity." (PMID 25844479, 2015). "The hormone leptin is known to play a critical role regulating the immune response in sepsis." (PMID 25844479, 2015). "According to these data we suggest that ghrelin has no direct effect on body temperature under inflammatory conditions like sepsis and higher ghrelin-induced leptin levels might outweigh a possible decreasing effect of the administered ghrelin." (PMID 25844479, 2015). "Despite a ghrelin-induced leptin elevation and the ability of leptin to generally improve cytokine response in sepsis the increase in TNFα with simultaneous IL-10 and IL-1ß decline may be a sign of suppression of an early and effective immune response." (PMID 25844479, 2015). "It is unclear whether ghrelin and leptin have antagonistic actions during host immune response during sepsis." (PMID 25844479, 2015). "In conclusion, leptin is a valuable marker for the diagnosis of sepsis." (PMID 24669245, 2014). "The exact mechanisms of leptin in sepsis require further study." (PMID 24669245, 2014).
Sepsis (continued). "Therefore, a prognostic model comprising a combination of leptin with temperature, platelet count, white blood cell count and heart rate was evaluated as an effective logistic regression model for the diagnosis of sepsis." (PMID 24669245, 2014). "Leptin has been reported to serve as an early biomarker of sepsis in patients, allowing differentiation between patients with systemic inflammatory response syndrome and patients with sepsis." (PMID 24578293, 2014). "The possible role of leptin in the prognosis of sepsis requires further study." (PMID 24669245, 2014). "The correlations between leptin and additional indicators of sepsis were evaluated." (PMID 24669245, 2014). "Furthermore, alterations in serum leptin and adiponectin have correlated with human survival in sepsis, although these relationships are complex and the investigations have been small." (PMID 23957291, 2013). "Therefore our observations support evidence that leptin appears to be involved in the pathogenesis and the course of a systemic inflammatory response during sepsis." (PMID 22973876, 2012). "However, in patients treated with DAA leptin serum levels increased from day 1 to day 3 day of severe sepsis during the infusion of DAA over 96 hours." (PMID 22973876, 2012). "In accordance with recently published data we could demonstrate increasing levels of leptin in patients suffering from severe sepsis compared to healthy controls and showed several correlations with established clinical markers of sepsis." (PMID 22973876, 2012). "This study aims to investigate leptin expression in cultured human adipocytes within an inflammatory model and in patients suffering from severe sepsis and evaluates treatment effects of drotrecogin alpha (activated) (DAA), the recombinant form of human activated protein C." (PMID 22973876, 2012). "This study investigated the expression of leptin both – in vitro – within an inflammatory model of human cultured adipocytes and – in vivo – in patients suffering from severe sepsis and additionally evaluated the specific treatment effect of drotrecogin alpha (activated) (DAA)." (PMID 22973876, 2012). "The role of leptin in sepsis and septic shock is still controversially discussed." (PMID 22272381, 2012). "From day 1 to day 3 of sepsis, leptin levels increased in DAA+ compared to DAA- patients (p<0.10)." (PMID 22973876, 2012). "LEP increases T-helper cells-1 (Th1) and suppresses Th2 cytokine production, hence its rise in sepsis promotes the host's pro-inflammatory response against its aggressors, and the lack of increase observed favours an anti-inflammatory pattern with an unfavourable outcome." (PMID 21943151, 2011). "Leptin concentrations are increased during infection and sepsis, in accordance with the observation that leptin expression is up-regulated by various pro-inflammatory cytokines, including tumor necrosis factor-α (TNF-α), interleukin-1 (IL-1) and leukaemia inhibitory factor." (PMID 21040518, 2010). "The role of leptin in sepsis and septic shock is controversial." (PMID 20825686, 2010). "In addition, previous studies reported different results related to leptin in sepsis." (PMID 34154308, 2021). "Similarly, serum leptin levels were significantly higher in sepsis survivors." (PMID 33123579, 2020). "Studies in clinical sepsis and/or animal models have identified impaired activity of hormones that are known to affect metabolism (e.g., insulin, glucagon, T3/4, growth hormone, epinephrine/norepinephrine cortisol) and of less well-studied endocrine agents (adiponectin, leptin, ghrelin)." (PMID 32676795, 2020). "Our data suggest that leptin-induced S100A9 overexpression exerts beneficial actions; yet, this idea is at odds with the fact that S100A9 forms a complex with S100A8, namely calprotectin, that has been shown to exert several deleterious effects including underlying sepsis-induced lethality." (PMID 31391467, 2019).